CRP (C-reactive protein)
Diseases named in the same sentence as CRP in open-access papers (continued):
Sharing a sentence is not in itself a finding about the gene and the disease.
COVID-19 (continued). "The severe disease course of COVID-19 was defined by CRP concentrations higher than 100 mg/mL, the requirement for oxygen therapy, and visible infiltrates on the chest X-ray." (PMID 36769843, 2023). "CRP was previously reported as a robust indicator of disease severity in COVID-19 patients, serving as a significant indicator of fatalities in individuals diagnosed with COVID-19." (PMID 38069113, 2023). "In particular, a recent research performed on diabetic patients confirmed that C-reactive protein (CRP) is a valuable predictor of COVID-19 progression and severity." (PMID 36380007, 2023). "In hematological patients, advanced disease, older age, type of malignancy, and several laboratory parameters, such as high CRP, lymphopenia, and neutropenia have been correlated with COVID-19 mortality." (PMID 37173883, 2023). "This is also associated with reduced C-reactive protein (CRP), which is an acute-phase protein that increases during inflammation and correlates with poor outcomes in COVID-19." (PMID 36851616, 2023). "Inflammatory markers implicated in the severity and prognosis of COVID-19 include increased Neutrophil-to-Lymphocyte ratio (NLR), C-reactive protein (CRP), and decreased Lymphocyte-to-C-reactive protein ratio (Lym-to-CRP)." (PMID 37391742, 2023). "High leukocyte count, low platelet count, high NLR, high CRP level, and high D-dimer on admission predicted mortality of COVID-19 patients." (PMID 37484181, 2023). "Age, scoring index of chest x-ray, percentage of neutrophils, and CRP showed a strong positive correlation with COVID-19 severity." (PMID 36668902, 2023). "While overlapping significantly between groups, VIP analysis suggested elevated CRP and thrombopenia to be associated with PIMS-TS more than active COVID-19." (PMID 38027272, 2023). "Clinical studies of COVID-19 patients were integrated, and the expression trend of serum CRP during the disease process was depicted." (PMID 38077346, 2023). "Wang measured the diameter of the largest lung infiltration on CT images, and assessed CRP on admission in 27 patients with COVID-19." (PMID 37165346, 2023). "Elevated levels of serum C-reactive protein have been observed in patients with COVID-19 and have been used to aid in the following triage: diagnosis of infection, quantification of inflammatory status, and prognosis of the patients." (PMID 37623485, 2023). "In Pakistan, 78% of COVID-19 patients included in a study had elevated ferritin values, showing that the mean values of ferritin, D-dimers, CRP, and LDH were higher in patients with severe symptoms than in patients with mild or moderate symptoms." (PMID 37241099, 2023). "The ARI hubs provide an opportunity to bring diagnostics closer to patients through point-of-care testing for COVID-19, influenza, and blood tests, including C-reactive protein (CRP)." (PMID 37237721, 2023). "COVID-19 patients with attenuated postconvalescence richness presented higher levels of C-reactive protein (CRP) and disease severity during the acute phase, implying a strong association between intestinal dysbiosis and inflammatory responses in COVID-19." (PMID 37205106, 2023). "Both ACE-2 and IFITM-3 SNPs were amongst the highest determinants of COVID-19 severity, together with IL-6, CRP, D-dimer, ferritin, preexisting comorbidities, and age." (PMID 38155729, 2023). "Lower glomerular filtration rate, high serum lactate dehydrogenase, C-reactive protein (CRP), creatinine, D-dimer, procalcitonin, and IL-6 have been some the markers associated with mortality in hospitalized KTRs with COVID-19." (PMID 37025740, 2023). "In this study we found persistent elevation of multiple mediators – IL-6, TNFα, SAA, Tie-2, Flt1, PIGF, and CRP – and persistent depression of IL-7 and bFGF in patients recovering from COVID-19 several months following their acute infection." (PMID 36844209, 2023).
COVID-19 (continued). "U ovoj retrospektivnoj studiji uporedili smo prognostičku vrednost osnovnog nivoa NLR, jutarnjeg kortizola, feritina i C-reaktivnog proteina (CRP) među pacijentima sa teškim i ne-teškim COVID-19." (PMID 37814623, 2023). "Elevated CRP at acute COVID-19 largely resolved at USG1 (only one had elevated CRP), and completely resolved at USG2." (PMID 36949763, 2023). "C-reactive protein and lactate dehydrogenase were higher in the post-COVID-19 patients independent from the severity of the disease and lung fibrotic areas." (PMID 37373960, 2023). "During-COVID-19 CRP levels were positively correlated with during-COVID-19 wake times (p = 0.01) and times in bed (p = 0.008)." (PMID 38136035, 2023). "CRP levels further significantly correlate with the extent of lung involvement in chest CT findings of COVID-19 patients." (PMID 37626775, 2023). "Important clinical factors associated with in-hospital mortality in elderly COVID-19 patients were age, sex, DNR status, diastolic blood pressure, body temperature, GCS score, total bilirubin, and CRP." (PMID 36814202, 2023). "C-reactive protein (CRP), Tumor Necrosis Factor-α (TNF- α), interleukin-6 (IL-6), IL-8, CXCL10, peripheral inflammation biomarkers linked to COVID-19 severity, also predict sequelae, as well as Type I and Type III interferons (IFN)." (PMID 38235145, 2023). "To complement the principal findings of our study, we examined CRP and ESR levels to understand, in part, the inflammatory process, given that severe COVID-19 are associated with higher levels of both biomarkers." (PMID 35634398, 2022). "D-dimer and elevated CRP are highly predictive of VTE in critically ill patients with COVID-19 (98%)." (PMID 36286066, 2022). "These inflammatory indicators are crucial for evaluating and monitoring patients with acute and long-term COVID-19, notably CRP, which had lower p-values." (PMID 36614901, 2022). "Ferritin levels, D-dimer, and the inflammatory biomarker CRP were significantly higher in the severe and moderate COVID-19 groups compared to controls (P<0.001)." (PMID 35982898, 2022). "It is of particular importance since the information about the correlations between the lymphocyte subsets and levels of CRP in COVID-19 patients is extremely limited at the moment." (PMID 35603207, 2022). "Nevertheless, studies defend the usefulness of CRP for initiating antibiotics since they found that patients with COVID-19 and coinfection had higher levels than controls." (PMID 36046297, 2022). "TNF-, IL-2, IL-6, IL1B, IL7, IL10, IFN-, GCSF, CXCL10, CCL2, ferritin, D-dimer, fibrinogen, leukocytosis, and C-reactive protein (CRP) levels are significantly higher in critically ill COVID-19 patients." (PMID 35645351, 2022). "High CRP levels were reported in patients with COVID-19 and reported to be related to poor prognosis." (PMID 34493032, 2022). "Serum levels of IP-10, CRP, IL-10, IFNγ, IL-13, IL-17α, IL-23, IL-6 were particularly upregulated in COVID-19 patients compared to controls." (PMID 36554094, 2022). "Inflammatory markers such as the serum cytokines lactate dehydrogenase (LDH), ferritin, D-dimer, interleukin-6, and high sensitivity C-reactive protein (hs-CRP) are used as quantitative measures of the severity of COVID-19." (PMID 36475201, 2022). "High TLC, neutrophil count and CRP were also reported to be reliable parameters in COVID-19 among pregnant patients in a review article." (PMID 35371473, 2022). "Zinc protoporphyrin and its ratio to specific markers along with CRP and Hb were specifically used to compare the potential of ZnPP in discriminating severity of COVID-19." (PMID 35113876, 2022). "We screened the COVID-19 samples in three steps: initially, 3492 COVID-19 positive samples were selected with variant levels of LDH, CRP, D-dimer, lymphocytes, AST, ALT, CK, albumin, and procalcitonin compared to the reference values." (PMID 35997388, 2022).
COVID-19 (continued). "In conclusion, serum vitamin D was inversely correlated with inflammatory markers (ferritin, CRP, and D-dimer) which mean that participants with symptoms of COVID-19 had a high level of inflammatory markers and a low level of vitamin D." (PMID 35754946, 2022). "In the study by Acar et.al, the ratio of the number of lymphocytes in peripheral blood to the level of C-reactive protein was higher in patients who died from COVID-19 compared with survivors (0,03 and 0,36, p <0,05)." (PMID 35603207, 2022). "The marker of inflammation, C reactive protein, was also higher in the COVID-19 group, median 78 (5.5, 208.5) vs. 22.6 (15.4, 61.8), p = 0.02, as well as a tissue damage biomarker median, LDH 563 (446.5, 812) vs. 292 (275.7, 573.5), p = 0.01." (PMID 35407403, 2022). "Levels of C-Reactive Protein (CRP) were higher for COVID-19 positive participants, whilst lymphocyte and eosinophils levels were lower." (PMID 35831456, 2022). "Inflammatory organ damage can result among sick individuals with critical COVID-19 or patients having an extremely greater expression of inflammatory markers including ferritin, C-reactive protein (CRP), interleukin-1, and interleukin-6." (PMID 35242118, 2022). "Glutamine supplementation reduced the hospitalization period of COVID-19 patients, reduced serum levels of interleukin-1 β, hs-CRP and tumor necrosis factor-α, and increased appetite." (PMID 35406806, 2022). "Recent studies have reported that GML can reduce suspected cases of COVID-19 and reduce the C-reactive protein level in patients." (PMID 36034889, 2022). "Further, CRP levels correlate with worse prognosis in COVID-19 with an odds ratio of 18.9 and were proven to be a reliable marker for numerous deleterious processes, as, e.g., the need for mechanical ventilation." (PMID 35407564, 2022). "In female patients with COVID-19, 25(OH)D was inversely correlated with CRP (R = −0.51, p < 0.05), and borderline significant inverse correlations with IL-2 (R = −0.5, p = 0.06) and IL-17α (R = −0.36, p = 0.06) were observed." (PMID 36554094, 2022). "In conclusion, the nomogram (including age, dyspnea, lymphocyte count, CRP and IL-6) objectively and accurately prewarns the severe disease occurrence out of common type COVID-19 patients." (PMID 35037900, 2022). "Age, male sex, diabetes, active malignancy, white cell count, serum creatinine, hypoalbuminemia, C-reactive protein, and viral loads were independent predictors for hyponatremia in COVID-19 patients (P < 0.001, for all)." (PMID 36714113, 2022). "Our data also depicted the same findings of higher CRP predicting the oxygen requirement of COVID-19-infected patients, thus differentiating severe cases from mild-moderate cases." (PMID 35683357, 2022). "As a marker of severe infection and systemic inflammation, CRP levels were shown to be substantially higher in the early stages of infection in severe COVID-19 patients, even before CT scans revealed serious abnormalities." (PMID 36562867, 2022). "A study of 76 patients with COVID-19 showed that high PCT and CRP levels were associated with mortality." (PMID 35168674, 2022). "Serum CRP level is a crucial indicator of systemic inflammation and an important prognostic marker in patients with COVID-19." (PMID 35747751, 2022). "Both SA and CRP values at admission are predictive indicators of in-hospital clinical course in patients admitted with COVID-19." (PMID 35740416, 2022). "Upon closer examination of the laboratory values, COVID-19 severity was associated with higher NEWS score (P<0.0001), qSOFA score (P<0.0001), plasma CRP (P<0.0001), and D-dimer (P<0.05) in both DM– and DM+ groups." (PMID 35766706, 2022). "In a prospective cohort study comparing the prognostic role of inflammatory markers in COVID-19 and other respiratory infections, IL-6 and CRP are reported as the strongest predictors for ICU admission or death, at 30 days." (PMID 36142336, 2022).
COVID-19 (continued). "Even when compared to other inflammatory biomarkers, CRP concentration at admission to the hospital of COVID-19 patients correlated with disease severity and tended to be a good predictor of adverse outcomes." (PMID 35897672, 2022). "C-reactive protein (CRP) and lymphocyte count (Lym) are known to correlate with worse outcomes in COVID-19 patients." (PMID 36357394, 2022). "In two systematic reviews of 727 articles most frequent laboratory abnormalities in COVID-19 patients were the decreased albumin, high C-reactive protein (CRP), elevated lactate dehydrogenase (LDH), lymphopenia, and high erythrocyte sedimentation rate." (PMID 35096087, 2022). "The neutrophil-to-lymphocyte ratio (NLR), platelet-to-lymphocyte ratio (PLR), and C-reactive protein (CRP) of patients with COVID-19 were compared." (PMID 35456328, 2022). "A comparison between ROC curves was made in order to test the prognostic performance of NLR, D-NLR, PLR, and CRP for predicting in-hospital mortality of COVID-19 patients." (PMID 35456328, 2022). "They further found that patients with colorectal cancer and COVID-19 were more prone to lymphopenia with higher respiratory rates and high-sensitivity C-reactive protein levels than patients with COVID-19 alone." (PMID 35281819, 2022). "Jayanthy and colleagues evaluated the predictive performance of CRP in patients with COVID-19 and a subgroup of diabetes mellitus patients and demonstrated a discrimination of 0.72 in this subgroup." (PMID 35746755, 2022). "A retrospective study of 22 patients from Indonesia also reported elevated D-dimers, CRP, and ferritin levels, revealing impressive parallels to the proposed COVID-19 biomarkers." (PMID 35883640, 2022). "IL-1β, IL-6, IL-8, TNFα and CRP in the hospitalised patients with COVID-19 (n = 76) was higher (all p<0.0001) compared to the healthy volunteers." (PMID 35500008, 2022). "CRP, an acute-phase reactant produced by the liver in response to inflammation, is markedly elevated in COVID-19 patients." (PMID 35381033, 2022). "Here, we found that hyaluronan was markedly increased in patients with pulmonary lesions and significantly correlated to the clinical parameters for the prediction of COVID-19 severity, including lymphocytes, C-reactive protein (CRP), D-dimer, and fibrinogen." (PMID 35304437, 2022). "In this regard, previous studies highlighted several demographic characteristics and laboratory features as prognostic factors in COVID-19, including older age, presence of comorbidities, obesity, C-reactive protein (CRP), and D-dimer levels." (PMID 35669915, 2022). "A previous meta-analysis involving more than two thousand patients revealed significantly higher CRP levels among those who succumbed to COVID-19 than in survivors." (PMID 35885582, 2022). "CRP was elevated in more than 69% of COVID-19 patients; furthermore, 57% of patients maintained a higher CRP level than the normal range throughout the hospital stay." (PMID 35433742, 2022). "The odds ratios reflected the effect of that parameter on the probability that a patient had an HAI; the BMI, frailty index, C-reactive protein (CRP), and thrombocyte count at the COVID-19 diagnosis of the patient remained significant at predicting an HAI." (PMID 36298847, 2022). "It has been demonstrated that severe COVID-19 is associated with a significant elevation in both ESR and CRP levels in the early stages of the disease." (PMID 36267156, 2022). "CRP, ferritin, creatinine, and hs-cTnT were all significant mediators of the effect of sex on COVID-19-related mortality." (PMID 35548417, 2022). "A combination of WBC at admission and trajectories of CRP over 72 h allowed to exclude 46% of bacterial co-infections in COVID-19 patients." (PMID 36275812, 2022). "Regarding the laboratory parameters, analogous to the findings in pediatric patients with COVID-19, C-reactive protein is a marker that can predict the prognosis of COVID-19." (PMID 35626923, 2022).
COVID-19 (continued). "Those with an end-stage malignancy, low LYM count, or high CRP and ferritin levels should be monitored closely after the diagnosis of COVID-19." (PMID 36326337, 2022). "Inflammatory biomarkers, such as IL-6 and CRP, are predictive biomarkers in COVID-19 patients and were significantly increased in the SARS-CoV-2-positive group compared to the control group." (PMID 35064792, 2022). "C-reactive protein presented a higher value in COVID-19-positive patients and flu-positive patients, but the difference was not significant (p = 0.116)." (PMID 35806866, 2022). "The key inflammatory factors c-reactive protein and ferritin, reported in all the COVID-19 based studies as indicators for severe infection, exhibited increased levels in ICU admitted patients." (PMID 35852999, 2022). "According to a retrospective study conducted in Guizhou, China, elevated levels of CRP, an acute-phase reactant and a marker of inflammation, is a direct marker of increasing severity in COVID-19 patients." (PMID 36324350, 2022). "Both treatment modalities in our study managed to reduce the systemic inflammation of COVID-19 patients, as reflected by their substantial decreases in CRP and ferritin levels." (PMID 35707401, 2022). "Certainly, among patients with severe COVID-19, elevated values of procalcitonin, C-reactive protein, D-dimer, and lactic dehydrogenase have been found." (PMID 36006242, 2022). "These agree with the findings of the present study, which showed a significant increase in IL6, D-dimer, CRP, and serum ferritin in both patient groups as compared to controls and in patients with severe COVID-19 as compared to moderate cases." (PMID 36359290, 2022). "We demonstrated that bolus doses of cholecalciferol resulted in an increased serum 25(OH)D level, neutrophil and lymphocyte counts, and decreased CRP levels in the acute period of COVID-19." (PMID 35807783, 2022). "Our findings suggest that high CRP levels (≥ 2.75 mg/dL) and history of ICI administration within 90 days are risk factors for respiratory failure in COVID-19 patients with lung cancer." (PMID 36316726, 2022). "Additional objectives are to correlate this impact with the other inflammatory biomarkers of COVID-19 such as C-reactive protein (CRP), ferritin and D-dimer and explore its potential as a differentiating tool between the grades of COVID-19 severity." (PMID 35350852, 2022). "We included all RCTs comparing Omega-3 with a control group regarding their effect on the CRP levels in patients with COVID-19." (PMID 36064554, 2022). "For example, acute phase proteins (APPs) including serum amyloid A-1 (SAA1), SAA2, SAA4 and C-reactive protein (CRP) were increased in severe COVID-19 patients, indicating activation of inflammation and the complement system." (PMID 35686122, 2022). "When the mortality models were adjusted for age, gender, BMI, and C-reactive protein, CKD and T2D the observed association between vitamin D levels and a decrease in COVID-19 mortality persisted." (PMID 35155539, 2022). "In a consecutive series of 50 cases of Italian patients with COVID-19 who presented a prolonged hospital stay and a low PaO2/FiO2 ratio, lymphopenia, and elevated C reactive protein (CRP) and lactate dehydrogenase levels were reported." (PMID 36341268, 2022). "In order to better understand the relationship between adropin, COVID-19, and DM, we also analyzed the correlation between serum adropin levels and CRP (an inflammatory biomarker), D-dimer, and ferritin." (PMID 35703530, 2022). "Patients in the COVID-19 era group tended to have a lower blood urea nitrogen, low-density lipoprotein cholesterol and C-reactive protein level on admission." (PMID 35433881, 2022). "Collectively, we suggest a distinct signaling pathway and/or cells for the induction of NP from those of CRP and IL-6 in patients with COVID-19." (PMID 35529699, 2022).